IQGAP1 (IQ motif containing GTPase activating protein 1)
Diseases named in the same sentence as IQGAP1 in open-access papers (continued):
Sharing a sentence is not in itself a finding about the gene and the disease.
diabetes (4 papers, 2012 to 2025). "In diabetic kidney disease (DKD), a complication of long-term diabetes, IQGAP1 has been implicated in the progression of renal injury." (PMID 41035668, 2025). "Studies suggest that IQGAP1 plays a vital role in regulating metabolic homeostasis, fat cell function, and insulin sensitivity, with potential implications for diseases like obesity and diabetes." (PMID 41035668, 2025). "Here, we explore the potential mechanisms through which IQGAP1 influences metabolic disorders, with a focus on its regulation of key metabolic pathways and its implications in diseases such as diabetes, obesity, cardiovascular disease, non-alcoholic fatty liver disease (NAFLD), and osteoporosis." (PMID 41035668, 2025). "Importantly, the receptor:IQGAP1 crosstalk has pathological implications ranging from diabetes and macular degeneration to carcinogenesis." (PMID 37071417, 2023). "Collectively, these data implicate IQGAP1 in insulin-mediated glucose regulation, suggesting it may be an appealing target for diabetes therapy." (PMID 37071417, 2023). "Studies on tissue sections from patients suffering from minimal change disease, focal and segmental glomerulosclerosis or diabetes may be interesting to clarify the putative role of IQGAP1 in pathogenesis." (PMID 22662192, 2012). "Furthermore, IQGAP1’s role in cellular metabolism and energy balance suggests its potential as a target for metabolic disorders, such as obesity and diabetes, where its involvement in signaling pathways related to insulin resistance and cell survival is critical." (PMID 41035668, 2025). "Additionally, IQGAP1 localizes to the same subcellular regions as SigmaR1, including the plasma membrane, the nuclear envelope and the ER, and is involved in similar disease outcomes such as cancer and diabetes." (PMID 37444574, 2023).
head and neck cancer (4 papers, 2020 to 2025). A primary or metastatic malignant neoplasm affecting the head and neck. "Given the critical role of the IQGAP1/PI3K pathway in the development of head and neck cancer, IQGAP1 has emerged as a potential therapeutic target for controlling this type of cancer." (PMID 41035668, 2025). "In general, IQGAP1 is not frequently mutated in cancer, with the possible exception of head and neck cancer." (PMID 34439095, 2021). "Moreover, the overexpression of IQGAP1 correlates with a higher number of TAMs in head and neck cancers, indicating the possibility that IQGAP1 could be contributing to carcinogenesis by promoting infiltration of TAMs." (PMID 34439095, 2021).
non-small cell lung carcinoma (4 papers, 2014 to 2023). A group of at least three distinct histological types of lung cancer, including non-small cell squamous cell carcinoma, adenocarcinoma, and large cell carcinoma. "Coexpression of Dvl-1 and IQ-domain GTPase-activating protein 1 (IQGAP1) in the cytoplasm and nucleus is closely related to the poor prognosis of non-small-cell lung cancer." (PMID 36726071, 2023). "In non-small cell lung cancer, the cytoplasmic and nuclear expressions of IQGAP1 were correlated with lymph node metastasis and poor overall survival." (PMID 33498739, 2021). "We used immunohistochemistry to assess the expressions of IQGAP1 and Dvl in a cohort of 111 non-small cell lung cancer (NSCLC) patients." (PMID 25436461, 2014). "Therefore, we assessed phosphorylation of endogenous IQGAP1 in non-small cell lung carcinoma (NSCLC) cell lines where MET signaling is up-regulated." (PMID 33087447, 2020).
ovarian tumor (4 papers, 2008 to 2023). "Upon signaling through integrins or endothelin-1, a key regulator of ovarian tumor progression, IQGAP1 forms a signaling complex with RacGAP1, which inactivates Rac but activates RhoA, thereby promoting the formation of invadopodia." (PMID 34439095, 2021). "This was consistent with previous findings that down-regulation of IQGAP1 by IQGAP1-specific siRNAs effectively blocks HA-CD44-stimulated SK-OV-3 ovarian tumor cell migration." (PMID 19036171, 2008). "Cells at the invasive front of colorectal and ovarian tumors have more IQGAP1 staining, especially at sites of intercellular contacts, than central tumor and normal cells, indicating that IQGAP1-mediated AJ disruption may drive tumor invasion." (PMID 37071417, 2023). "Notably, upregulated IQGAP1 levels are detected in tumour budding foci at the invasive front of colorectal and ovarian tumours compared to central tumour regions and normal tissues, suggesting a critical role of IQGAP1 in tumour invasion and metastasis." (PMID 32632148, 2020).
Sepsis (4 papers, 2019 to 2025). Sepsis is defined as life-threatening organ dysfunction caused by a dysregulated host response to infection. "PDGFR-β:IQGAP1 similarly enhances migration of both VSMCs and VE cells during sepsis, revealing functions in the repair of sepsis-associated vascular damage." (PMID 37071417, 2023). "Taken together, our results suggest that the PDGFRβ/PI3K/Akt/IQGAP1 pathway is an important regulator in the recovery process induced by LPS injury and therefore plays a critical role in vascular injury during sepsis." (PMID 31576676, 2019). "However, the effects of IQGAP1 on SMC phenotypic transformation and migration following vascular damage caused by sepsis remain unknown." (PMID 31523178, 2019). "The present study investigated the role of the PDGFRβ/IQGAP1 pathway in EC-mediated SMC phenotypic transformation and migration during sepsis in a co-culture cell model." (PMID 31523178, 2019).
squamous cell carcinoma (4 papers, 2014 to 2023). A carcinoma arising from squamous epithelial cells. "The present study investigated the IQGAP1 and Dvl expression of NSCLC (adenocarcinoma and squamous cell carcinoma)." (PMID 25436461, 2014). "Moreover, deletion of the third of four IQ motifs (IQ3) from IQGAP1 abrogates binding to PI3K/Akt, which reduces EGF-stimulated migration and invasion of squamous carcinoma cells." (PMID 37071417, 2023).
gastric adenocarcinoma (3 papers, 2016 to 2024). "In gastric adenocarcinoma-derived cell lines, menin expression was also found to downregulate the expression of IQ motif containing GTPase-activating protein 1 (IQGAP1)." (PMID 39336822, 2024). "Our results indicate that alterations in IQGAP1 signalling promote the emergence of CSCs and gastric adenocarcinoma development in the context of an H. pylori infection." (PMID 27729612, 2016).
Obesity (3 papers, 2022 to 2025). Accumulation of substantial excess body fat. "For the identified DEHGs for obesity, there were six previously reported genes (UGGT1, ANO6, MPEG1, PTGS1, CLU and IQGAP1) and two novel genes (LUZP6 and PLCB2) for obesity." (PMID 35568907, 2022).
oral cancer (3 papers, 2019 to 2024). "It is possible that only VAV2 or IQGAP1 mutation is responsible for the development of oral cancer in the family." (PMID 31798960, 2019). "Here, we analyzed whole-genome sequences of a family with autosomal dominant expression of oral tongue cancer and identified proto-oncogenes VAV2 and IQGAP1 as the primary factors responsible for oral cancer in the family." (PMID 31798960, 2019). "In this study, we identified VAV2 and IQGAP1 as the genetic basis of a case of oral cancer in a family." (PMID 31798960, 2019). "Taken together, these results strongly suggest that the mutations associated with the oral cancer family stimulate the oncogenic activity of VAV2 and IQGAP1." (PMID 31798960, 2019). "Similarly, VAV2 (91%), IQGAP1 (91%), and KIAA0556 (100%) were the most frequently mutated genes in the oral cancer cell lines JHU12, PC130, SCC15, and SCC2095, as well as in seven sporadic oral cancer cases without paired normal tissue controls." (PMID 31798960, 2019). "We also noted that some of the previously identified OSCC genes are also mutated in certain members of the oral cancer family, but they are not as dominantly penetrated as IQGAP1 and VAV2 in the family." (PMID 31798960, 2019).
pancreatic ductal adenocarcinoma (3 papers, 2019 to 2024). An infiltrating adenocarcinoma that arises from the epithelial cells of the pancreas. "However, the role of IQGAP1 in pancreatic ductal adenocarcinoma (PDAC) is still unknown." (PMID 31101875, 2019). "Additionally, FBP1's binding to the WW domain of IQ motif containing GTPase-activating protein 1 (IQGAP1) blocks IQGAP1-dependent ERK1/2 phosphorylation, leading to an enhanced anticancer response to gemcitabine in pancreatic ductal adenocarcinoma." (PMID 38349431, 2024).
viral infection (3 papers, 2019 to 2021). "On the other hand, SDC4, PIK3CA, and IQGAP1 genes showed upregulated expression upon viral infection, and after mimic transfection and infection, their expression levels were decreased in hNP cells." (PMID 31578247, 2019). "The timing of IQGAP1-mediated signaling in viral infection and tumor formation might also explain the difference between the two models." (PMID 34068608, 2021).
Arthritis (2 papers, 2019 to 2024). Inflammation of a joint. "Inactivating IQGAP1 normalized Rac1 GTP-loading and reduced inflammation and arthritis in GTPase-I-deficient mice, preventing statins from increasing Rac1 GTP-loading and cytokine production in macrophages." (PMID 38791282, 2024). "Knockout of Iqgap1 normalized Rac1-GTP loading, abolished proinflammatory signaling and cytokine production, and markedly reduced arthritis in GGTase-I-deficient mice." (PMID 31484924, 2019). "Consistently, inactivating Iqgap1 normalizes Rac1 GTP-loading, and reduces inflammation and arthritis in GGTase-I-deficient mice, as well as prevents statins from increasing Rac1 GTP-loading and cytokine production in macrophages." (PMID 31484924, 2019). "Whether or not Iqgap1 influences Rac1-GTP signaling and cytokine production in arthritis and other inflammatory diseases in the setting of wild-type GGTase-I remains to be determined." (PMID 31484924, 2019).
atherosclerosis (2 papers, 2017 to 2025). A disease characterized by the build-up of fatty material and calcium deposition in the arterial wall resulting in partial or complete occlusion of the arterial lumen. "In summary, our research established that IQGAP1 is an important factor that leads to apoptosis of endothelial cells and atherosclerosis in the aorta of mice." (PMID 40658677, 2025). "Future studies employing IQGAP1/YAP double knockout murine models should be conducted to dissect their synergistic mechanisms in atherosclerosis development." (PMID 40658677, 2025). "Finally, we have also provided some preliminary but clear evidence to suggest a role of hnRNPA1/miR-124/IQGAP1 regulatory axis in human angiographic restenosis or atherosclerosis." (PMID 28912364, 2017). "However, the regulatory mechanism between IQGAP1 and endothelial cell apoptosis in atherosclerosis is not yet clear." (PMID 40658677, 2025).
cholestasis (2 papers, 2018 to 2021). Impairment of the bile flow caused by obstruction within the liver, or outside the liver in the bile duct system. "In addition, increased Ki67 levels are reported upon IQGAP1 overexpression whereas Ki67 positive cells were reduced in Iqgap1 knockout mice upon CA diet which induces cholestasis." (PMID 30501048, 2018). "In addition, increased IQGAP1 and nuclear YAP localisation have been reported in human biliary disorders and bile duct ligated mice, a model for experimentally induced cholestasis." (PMID 30501048, 2018).
Cirrhosis (2 papers, 2009 to 2010). A chronic disorder of the liver in which liver tissue becomes scarred and is partially replaced by regenerative nodules and fibrotic tissue resulting in loss of liver function. "By IHC, IQGAP1 was detected in the hepatocytes of 5/28 (17.9%) normal livers, 0/4 (0.0%) hepatic adenomas and 0/23 (0.0%) cirrhosis cases." (PMID 20977743, 2010). "No IQGAP1 staining was detected in 23/28 (82.1%) normal livers, 4/4 (100.0%) hepatic adenomas and 23/23 (100.0%) cirrhosis cases, while IQGAP2 was increased in 22/28 (78.6%), 4/4 (100.0%) and 23/23 (100.0%), respectively." (PMID 20977743, 2010). "Indeed, 84.1% of HCCs were positive for IQGAP1, whereas all hepatic adenomas, cirrhosis cases, and most (82.1%) normal livers were IQGAP1 negative." (PMID 20977743, 2010).
clear cell renal cell carcinoma (2 papers, 2020 to 2022). "We observed associations of IQGAP1 downregulation with poor overall survival (OS) in clear cell renal cell carcinoma (ccRCC)." (PMID 33266355, 2020). "We have recently constructed a novel and effective multigene prognostic panel for clear cell renal cell carcinoma (ccRCC) based on the network of IQGAP1." (PMID 35681785, 2022).
COVID-19 (2 papers, 2024). A disease caused by infection with severe acute respiratory syndrome coronavirus 2. "In contrast, COVID-19 may deactivate the IQGAP1-mediated vascular maintenance, increasing the risk of stroke." (PMID 39469068, 2024). "While ARG1 and ACSL1 were upregulated in both diseases, IQGAP1 was downregulated in COVID-19 but upregulated in IS." (PMID 39469068, 2024). "We also observed a suggestive association with rs2601183 in chromosome 15, which is located between ZNF774 and IQGAP1 (allele-G OR = 1.20, 95% CI = 1.12–1.29, p=6.11 × 10–8), which has not yet been reported in any other GWAS of COVID-19 to date." (PMID 39361370, 2024). "The lowest number of the common DEGs was observed between COVID-19 and IS, including ARG1, ACSL1 and IQGAP1." (PMID 39469068, 2024).
endometrial cancer (2 papers, 2000 to 2016). Primary or metastatic malignant neoplasm involving the endometrium (mucous membrane that lines the endometrial cavity). "We demonstrate that IQGAP1 activates the epithelial–mesenchymal transition (EMT) program and that miR-124 directly represses IQGAP1 expression in endometrial cancer (EC) cells." (PMID 26934121, 2016).
esophageal cancer (2 papers, 2021 to 2022). A primary or metastatic malignant neoplasm involving the esophagus. "Disrupting IQGAP1′s expression reduced the malignant phenotypes in both laryngeal and esophageal cancer cells." (PMID 34439095, 2021). "IQGAP1 contributes to esophageal cancer by promoting the angiogenesis process through AKT and ERK activation." (PMID 34439095, 2021). "At the same time, IPO5 can regulate the transcription of IQGAP1 protein, so we speculated that IPO5 can promote the progression of esophageal cancer through the RAS pathway." (PMID 36120598, 2022).
esophageal squamous cell carcinoma (2 papers, 2021 to 2025). Esophageal squamous cell carcinoma (ESCC) is a type of esophageal carcinoma (EC) that can affect any part of the esophagus, but is usually located in the upper or middle third. "In esophageal squamous cell carcinoma (ESCC), IQGAP1 enhances resistance to paclitaxel (PTX) by upregulating the Hippo pathway downstream effector YAP." (PMID 41035668, 2025).
Hypercholesterolemia (2 papers, 2015 to 2021). An increased concentration of cholesterol in the blood. "Ras GTPase-activating-like protein IQGAP1 was identified and validated as a hypercholesterolemia-induced metastasis-associated protein." (PMID 25924234, 2015). "In addition to IQGAP1, it is likely that other cholesterol-rich membrane microdomain-associated proteins are altered by hypercholesterolemia to impact on tumor metastasis." (PMID 25924234, 2015). "We performed Western blotting of both xenograft tumor and cell lysates to determine the effect of hypercholesterolemia on the expression of level of caveolin-1 and IQGAP1." (PMID 25924234, 2015). "Next, we investigated if hypercholesterolemia altered membrane localization of IQGAP1, which mediates cell migration." (PMID 25924234, 2015). "Down-regulation of caveolin-1 or IQGAP1 in PC-3 cells reduced migration and invasion in vitro, and hypercholesterolemia-induced metastasis in vivo." (PMID 25924234, 2015). "Taken together, these results suggest that IQGAP1 and caveolin-1 potentiate PC-3 metastasis, and that the elevation of IQGAP1 levels in hypercholesterolemia plays an important role in metastasis." (PMID 25924234, 2015). "We demonstrate that diet-induced hypercholesterolemia promotes orthotopic xenograft PC-3 cell metastasis, concomitant with elevated expression of caveolin-1 and IQGAP1 in xenograft tumor tissues." (PMID 25924234, 2015). "We further demonstrate the involvement of two proteins, caveolin-1 and IQGAP1 in hypercholesterolemia-induced xenograft tumor metastasis in vivo." (PMID 25924234, 2015). "Hence, we tested the hypothesis that hypercholesterolemia increases IQGAP1 protein at the transcriptional level using qPCR." (PMID 25924234, 2015). "Surprisingly, IQGAP1 mRNA was not responsive to cholesterol or oxysterol treatment in PC-3 and LNCaP cells, indicating that hypercholesterolemia increases IQGAP1 protein at a post-transcriptional level." (PMID 25924234, 2015). "Our results show that hypercholesterolemia increases the level of both proteins in the DRF fraction, but it is not clear whether caveolin-1 and IQGAP1 actually co-localize to the same membranes." (PMID 25924234, 2015).